CD4 (CD4 molecule)
Diseases named in the same sentence as CD4 in open-access papers (continued):
Sharing a sentence is not in itself a finding about the gene and the disease.
tumor (continued). "Interestingly, CTLA-4 blockade loses efficacy in CD4+ T cell-depleted mice, suggesting its anti-tumor effects rely on CD4+ T cell-mediated modulation of dendritic cells and microglia, offering new insights into its role in GBM treatment." (PMID 39911397, 2025). "Genetic inhibition of endothelial autophagy in these mice led to remodeling of the aberrant tumor vasculature, resulting in a significant increase in functional tumor blood vessels and a marked elevation in the overall density of CD8+ and CD4+ T cells within the tumor stroma." (PMID 39744218, 2025). "Additionally, the T cell population in all tumor lesions in both infected groups was composed of approximately 95% of CD4+ T cells, including a phenotype expressing mTGF-β, and the percentages of CD8αβ+ T cells and γδ T cells were less than 1%." (PMID 40673706, 2025). "Overexpression of CD27 within CD4+ T cells may suppress anti‐tumor immunity by enhancing regulatory T cell (Treg) function." (PMID 41057994, 2025). "Circulating tumor-TCR-matching CD4+ T cells are predominantly cytotoxic." (PMID 40299576, 2025). "Furthermore, the positive relationship of PCSK1N with activated NK and CD4 memory T cells reinforces its potential role in fostering anti‐tumor immunity." (PMID 40600620, 2025). "Anti-CTLA-4 may exert its anti-tumor effects by increasing the activity of effector CD4+ T cells and inhibiting the Tregs-dependent immune suppression." (PMID 40861801, 2025). "Additionally, immunofluorescence co-staining revealed significant infiltration of CD4+Foxp3+ regulatory T cells within the tumor immune microenvironment of CNS GCTs, providing initial evidence of an immunosuppressive state in these tumors." (PMID 39958339, 2025). "Tumor B cells were found to stimulate both CD4 and CD8 T cells via CD86–CD28 and CD70–CD27." (PMID 40571973, 2025). "Concurrently, CD4+ T cells are regarded as anti-tumor effector cell." (PMID 41030456, 2025). "In addition to targeting CAFs, PEG-SAB-Lip also enhances the anti-tumor effects of docetaxel and significantly increases the expression of CD4+ and CD8+T cells." (PMID 40038745, 2025). "Notably, researchers found that tumor-interacting CD4+ T cells showed higher LAG3 expression than CD8+ T cells and LAG3 showed strong binding affinity for MHC-II." (PMID 41425696, 2025). "Moreover, we also observed a significant elevation in the numbers of tumor-infiltrating CD4 + and CD8 + T cells in the combination group." (PMID 39810240, 2025). "Specifically, activated CD4 + T cells and CD56dim NK cells were enriched in tumor tissues." (PMID 40577282, 2025). "Rasing TAGAP could rejuvenate the toxicity of CD4+ T cells and inhibit the tumor progress in vitro and in vivo, and vice versa." (PMID 39998561, 2025). "Additionally, IHC analysis corroborated the flow cytometry findings and showed increases in staining of CD8+ and CD4+ T cells, NK cells (NKp46), and macrophages (F4/80) in MerTK-overexpressing tumor sections relative to Vector control." (PMID 40391157, 2025). "In humans and mice, priming of tumor-specific CD4+ T cells primarily occurs in tdLNs." (PMID 41030446, 2025). "These CD4+ T lymphocytes are pivotal in orchestrating anti-tumor immune responses in humans." (PMID 41268299, 2025). "SIGLEC9+CD4+T-cells infiltrated around the tumor nests, and MUC1 was expressed in the tumor nests." (PMID 41418390, 2025). "Disrupting the interaction between CTLs and CD4+ T cells through HLA-DR blockade or CD4+ T cells depletion may compromise anti-tumor immune responses, suggesting a critical role for both HLA-DR and CD4+ T cells in CTLs activation and cytotoxic capabilities." (PMID 41050699, 2025). "In tumor explants, sClever-1 bound to activated CD4+ and CD8+ T cells and increased TGFβ secretion." (PMID 40756372, 2025). "Interestingly, we observed a positive correlation between SAS and resting memory CD4+ T cells in several tumor types." (PMID 41441975, 2025).
tumor (continued). "Moreover, both tumor groups showed diminished OS upon depletion of both CD4+ and CD8+ cells than was the case for depletion of CD8+ cells alone, indicating a CD8+ T cell-independent anti-tumor effect of CD4+ T cells." (PMID 39835538, 2025). "Interestingly, PD-1-positive CD4 + T cells are also enriched in tumor tissues and present in metastatic tissues, suggesting their potential role in disease progression." (PMID 41035074, 2025). "Although detectable quantities of CD8+ cytotoxic T cells, CD4+ helper T cells, and immunosuppressive Tregs are present, their distribution is largely restricted to the tumor’s infiltrative margin; they are observed to be extremely scarce within the tumor core." (PMID 41463052, 2025). "Additionally, we observed that two types of immune cells—M0 macrophages and resting memory CD4 T cells—had the highest estimated proportions in tumor samples." (PMID 39744570, 2025). "Traditional studies in solid tumors have shown that CD4 TH cells sustain anti‐tumor activity by directing other leukocytes, enhancing tumor‐antigen presentation, and directly inhibiting tumor proliferation via interferon gamma (IFN‐γ) and tumor necrosis factor alpha (TNF‐α)." (PMID 40571973, 2025). "However, tumor-specific CD4+ T helper cells are necessary for the activation and persistence of these CD8+ T cells, and their presence is necessary for their effective operation." (PMID 41018485, 2025). "Post-neoTx tumours showed higher CD4+, CD8+, and CD45RO+ T cell densities and lower mTLS presence." (PMID 41265130, 2025). "In summary, our data show that particularly the expression of MATEs by the oncolytic virus promote the interaction of CD8 T cells not only with tumor cells to exert their cytotoxic function but may also promote interaction of CD4+ and CD8+ T cells." (PMID 39789356, 2025). "More importantly, the CD8+ T and CD4+ T cells in distant tumors were significantly activated in distant tumor when WO2.9-WSe2-PEG nanoparticles combined with RT/PTT and anti-PD-L1 antibody, indicating powerful immunological memory-killing and efficiently antimetastatic and anticancer effect." (PMID 40017598, 2025). "The key question is whether MYXV influences or even subverts immunosuppression by CD14+ TAMs to enable a more effective anti-tumor CD4+ T cell response." (PMID 40872773, 2025). "Based on their characteristics, TILs can be classified into cellular subgroups, such as CD8+ T lymphocytes, tissue-resident memory T lymphocytes, CD4+ helper T lymphocytes, CD4+ regulatory T lymphocytes, CD4+ follicular helper T lymphocytes, and tumor-infiltrating B lymphocytes." (PMID 41516015, 2025). "The depletion of CD4+ T cells also significantly decreased the survival of saline-treated mice (P = 0.002) lowering their median survival to 45.5 days post-tumor implantation, which was significantly shorter than M002-treated mice with CD4+ T-cell depletion (P = 0.006)." (PMID 39885128, 2025). "Notably, five of the six patients who relapsed within 1 year after surgery were classified as having T cell–deserted tumors on-treatment, and all patients with NSCLC exhibited low CD4+ T cell densities within the tumor core." (PMID 40561008, 2025). "First, histological examination of tissues 42 days after treatment confirmed that while mice treated with the triple combination (and an IgG2b control) exhibited evidence of residual tumor cells, those treated with the triple combination and a CD4-depleting antibody showed clear tumor outgrowth." (PMID 40299790, 2025). "The broad immunosuppressive state in HRG (such as down-regulated functions of activated CD4 T cells and natural killer T cells) might promote tumor immune escape, suggesting that immunotherapy might have limited efficacy in HRG patients." (PMID 40895068, 2025). "In another study focusing on the anti-tumor potential of T cell-derived EVs, miRNAs such as miR-25–3p, miR-155–5p, miR-215–5p, and miR-375 were found to be enriched in EVs secreted from IL-2-stimulated CD4+ T cells." (PMID 40400306, 2025).
tumor (continued). "We next performed anti-CTLA-4 therapy in tumor-bearing mice depleted of CD4+ T cells." (PMID 40460830, 2025). "Similarly, tumor-infiltrating CD4+ and CD8+ T cells displayed increased PD-1 and CD39 expression, hallmarks of immune exhaustion, particularly in eHCC." (PMID 40547009, 2025). "However, Treg, a typical CD4+ T cell subset, have also been found to support tumor progression and promote tumor persistence and metastasis." (PMID 40385461, 2025). "While primary CD4+ T cells showed similar trends in experiments, patient-derived BL cells and tumor microenvironment conditions might reveal additional layers of regulation." (PMID 40801653, 2025). "Using the same 4T1 tumor mouse model with the same treatment schedule, we excised tumors right after treatment to assess TILs, including CD4 + T cells, CD8 + T cells, macrophages, monocytic-myeloid-derived suppressor cells (M-MDSCs), and regulatory T cells (Tregs) under various treatment conditions." (PMID 40836337, 2025). "To further validate our immune cell estimation based on proteomics and immune gene signatures, we examined the infiltration of CD56+CD3- NK cells, CD56+CD3+ NKT cells, and CD4+ T cells in five paired eCCA tumor and adjacent normal tissues by immunofluorescence staining." (PMID 41061966, 2025). "After ICI treatment, CD4+ T cells release interleukin-5 (IL-5), stimulating eosinophil production in the bone marrow, which subsequently leads to their accumulation in peripheral blood and infiltration into tumor tissues." (PMID 39949762, 2025). "Activated CD4 + T cells are crucial for anti-tumor immune responses." (PMID 41003841, 2025). "Whether cryptic proteins constitute a class of tumour antigens presented on MHC‐II for recognition by CD4+ T cells remains to be determined." (PMID 41416931, 2025). "Further, CD4+ T cell depletion by specific antibodies also abrogated the tumor growth difference between WT and Gsdmd–/– mice, and, notably, comparable tumor infiltration and IFN-γ production by CD8+ T cells were detected." (PMID 40759573, 2025). "Furthermore, MIF downregulates MHC class II, implying that it also hinders the presentation of tumor antigens to CD4+ T cells." (PMID 41159021, 2025). "Additionally, tumor cell-secreted Gal-1 can increase CD4 + CD25 + Foxp3 + Treg cells, promoting an immunosuppressive microenvironment in breast cancer." (PMID 40134029, 2025). "Hence, co-localisation of monocytes/macrophages and CD4+ T cells coincided with CXCL9/CXCL10 expression in human tumours." (PMID 40523200, 2025). "In GBM, LSM2 could promote neutrophil infiltration while inhibiting CD4+ T cell infiltration, which may facilitate immune evasion by the tumour." (PMID 40365337, 2025). "CD4+ lymphocytes are responsible for the elimination of intra- and extracellular pathogens, and clearance of tumours which evade cytotoxic CD8+ lymphocytes and are therefore critical in the immediate post-operative period to prevent both infections and tumour recurrence in cancer surgery." (PMID 41148718, 2025). "This suggests that the potential partnership between CD56dim NK cells and CD4+ T cells could be critical especially when the LGG tumours are evading the CD8+ T cells." (PMID 40361496, 2025). "Other contributing factors may include immunosuppressive cytokines (e.g., interleukin-10, TGF-β), metabolic stress within the tumor microenvironment, hormonal influences, and insufficient CD4+ T-cell help during early priming." (PMID 40723153, 2025). "Tumor cells can be prepared into lysates, which also allows the loading of a wide variety of antigens to DCs to ensure maturation, and are capable to induce both CD4+ and CD8+ T cell response." (PMID 40491907, 2025). "Notably, cancer cells exploit trogocytosis to acquire immune regulatory molecules such as CD45, CD4 and checkpoint proteins, effectively dampening anti-tumor responses while enhancing their own survival." (PMID 41181711, 2025).
tumor (continued). "To determine whether Treg depletion unleashes an anti-tumour immune response to ApcΔISC, through induction of IFNγ-producing, Granzyme B + T cells capable of killing ISCs7,8 we administered CD4 or CD8 depleting antibodies." (PMID 39877864, 2025). "This phenomenon may result in the stimulation of immunosuppressive CD4+ Treg cells that may act as an immune evasion mechanism and favor tumor growth." (PMID 40573917, 2025). "Interestingly, blocking CD4+ T cells increased tumor growth, suggesting CD4+ T cells support CD8+ T cell cytotoxicity." (PMID 40606756, 2025). "The direct contribution of CD4+ T cells to tumor killing has recently attracted more attention." (PMID 39885128, 2025). "Further analysis of scRNA-seq of CD4+ T cells in isolation revealed two clusters (labelled “E” and “F”), that were predominantly newly recruited Kaede-green cells and almost exclusively present in anti-PD-L1-treated tumours." (PMID 40523200, 2025). "This decrease in TXNIP gene expression level in tumor was also observed within each CD4+ T cell subtype, indicating that this decrease not only results from changes in main cell subtypes composition but also from intrinsic transcriptomic adaptation to tumor micro-environment." (PMID 40260243, 2025). "Low expression of IL‐11 in tumour cells was associated with significantly higher levels of leukocytes (CD45), T cells (CD3, CD4, CD8), T‐cell activation (CD44, CD25, ICOS, Tim3), dendritic cell activation, antigen presentation (CD11c, CD80, B2M, HLA‐DR) and macrophage (CD68) markers." (PMID 40673604, 2025). "In addition, in the tumour microenvironment, activated CD4+ T cells enhance CD8+ T cell priming, facilitate dendritic cell licensing, and contribute to the formation of tertiary lymphoid structures, thereby amplifying immune surveillance and effector function." (PMID 40673641, 2025). "In this study, we found that cDHPs inhibited the growth of lung adenocarcinoma (LUAD) transplants in mice and prevented the conversion of CD4+ T cells into IL-35-producing induced regulatory T cells (iTr35) to activate anti-tumor immunity by inhibiting the FXR1-IL-35 axis." (PMID 40259042, 2025). "The high clonal expansion of CXCL13+ CD4+ T cells likely accounts for their increased proportion following D + T treatment compared to D alone, suggesting a role in enhancing anti-tumor effects." (PMID 41045934, 2025). "Additionally, our study showed an increased CD4+ T cell fraction in all 4 tumor entities, reaching statistical significance in BC and MM patient aspirates." (PMID 40274631, 2025). "Furthermore, osthole increases the tumor-infiltrating CD4+/CD8+ T cell ratio and elevates serum levels of IL-2 and TNF-α, while concurrently reducing the population of splenic regulatory Tregs." (PMID 40495147, 2025). "In lymph nodes, APCs present tumor-derived peptides to CD4+ T cells, initiating their activation." (PMID 40429961, 2025). "The demonstration of the increased Tconv CD4+ tumor suppressive phenotype in the presence of mtDNANZB Treg cells could result from loss of Treg numbers, impaired Treg function, or both." (PMID 39752523, 2025). "Notably, once DCs internalize tumor antigens, they can efficiently relay antigenic information to neighboring CD4+ T cells, thereby instigating the activation process of CD4+ T cells." (PMID 41035636, 2025). "Moreover, spatial clustering identified immune-rich and tumor-dominant neighborhoods, with the presence of effector CD4+ T cells in tumor regions correlating with improved survival outcomes." (PMID 40362187, 2025). "We further assessed whether ALK+ tumor cells expressing CD4 or CD8 also expressed CD44 or CD62L markers, usually used to distinguish naïve (CD62Lhigh CD44low), effector (CD62Llow CD44high) or central memory T cells (CD62Lhigh CD44high)." (PMID 40175628, 2025).
tumor (continued). "Moreover, the coupling of cDC1 and CD4 T cells via CD40 signaling in the presence of the proinflammatory cytokine IFN-gamma is a major source of cDC1 activation to cross-present tumor antigens to CD8 T cells in the context of MHC-I." (PMID 40333343, 2025). "CD4+ T cells are required for the tumor protective effect of calcipotriol-plus–5-FU immunotherapy." (PMID 39744942, 2025). "We identified different populations of CD8+ and CD4+ T cells within Antoni A and B regions, but what these populations interact with and if they occupy the same tumour subniches is unknown." (PMID 40140675, 2025). "Since ENO1 is expressed on the tumor cell surface as a whole protein, inducing CD4+ T cells, the vaccine may also induce citENO1-specific B cells, resulting in antibody-dependent cellular cytotoxicity (ADCC)." (PMID 40573960, 2025). "In addition to cytokine support, under specific conditions, CD4+ T cells can also exert direct cytotoxicity against tumor cells, similarly to CD8+ T cells." (PMID 40430079, 2025). "Since tumor-infiltrating CD4+ Tconv were highly expanded during treatment with 9D9, we hypothesized that they could play a role in the modulation of tumor blood vessels." (PMID 40460830, 2025). "The interaction between macrophages and ECs could regulate tumor inflammation and metastasis, and malignant ECs, in the cancer microenvironment, have been shown to inhibit CD4+ T cell activity." (PMID 39944338, 2025). "Notably, adoptive transfer of neoepitope-specific CD4+ T cells induced tumor regression in a cholangiocarcinoma patient, providing direct clinical evidence of the anticancer effectiveness of neoantigen-specific T cells." (PMID 41584608, 2025). "Furthermore, CD8 and CD4 T- cells in mixed tumor regions exhibit exhausted phenotypes characterized by elevated PD-1 expression." (PMID 41254766, 2025). "Each subset of CD4+ T cells can have both anti-tumor and pro-tumor functions." (PMID 41281743, 2025). "Indeed, increasing evidence highlights the importance of CD4+ T cell tumour surveillance and control through recognition on peptide MHC II complexes." (PMID 40351814, 2025). "Our results suggest that the beneficial effect we observe of increased expression of this gene on CRC may be related to enhanced antigen presentation to CD4+ T cells, consequently boosting anti-tumour immunity." (PMID 40321251, 2025). "Notably, the proportion of immunosuppressive Tregs (CD4+Foxp3+), on the other hand, decreased significantly, which is beneficial for enhancing overall anti-tumor immunity." (PMID 41383334, 2025). "The ssGSEA analysis showed that the infiltration of Type 17 T helper cells, neutrophils, activated B cells, Type 2 T helper cells, activated CD4 T cells, and activated CD8 T cells—immune cells typically involved in killing tumor cells —was lower in the high-risk group compared to the low-risk group." (PMID 40613523, 2025). "CD4+ memory T cells and Tfh cells are critical for maintaining and amplifying T cell immune responses, particularly playing an essential role in immune surveillance within the tumor microenvironment." (PMID 41179292, 2025). "Specifically, the study revealed that an increase in tertiary lymphoid structures within tumor lesions enhanced synergy between B cells and CD4+ T cells and that the conversion of B cells into an anti-tumor IgG class significantly amplified the anti-tumor immune response." (PMID 40003951, 2025). "In the clinical settings, it has been reported that tumor‐infiltrating CD4‐positive T lymphocytes, peripheral CD62 low CD4‐positive T lymphocytes, and peripheral CD4‐positive memory T lymphocytes are associated with the efficacy of immune checkpoint inhibitors in patients with NSCLC." (PMID 41187938, 2025). "Previous studies have posited that LMNB2 interacts with tumor immune cells, including B cells, CD8+ T cells, CD4+ T cells, and macrophages, and may be implicated in HCC progression." (PMID 40483310, 2025).